EZH2 (enhancer of zeste 2 polycomb repressive complex 2 subunit)
Diseases named in the same sentence as EZH2 in open-access papers (continued):
Sharing a sentence is not in itself a finding about the gene and the disease.
cervical carcinoma (continued). "High levels of EZH2 expression in HPV-positive cervical carcinomas and HPV E7 expressing cell lines and their apparent addiction to EZH2 is particularly remarkable since the H3K27me3 mark is decreased, not increased, in such cell lines." (PMID 23673719, 2013). "Cytotoxicity of the positive control drug cisplatin and two EZH2 inhibitors was evaluated by MTT assay on two cervical cancer cell lines (HPV- C33a; HPV+ CaSki) and non-cancerous epithelial cell line following 48 h drug exposure." (PMID 41614754, 2025). "This study aimed to investigate whether EZH2 inhibitors (EPZ6438 and ZLD1039) can be effective in managing cervical cancer with less toxic effects than the conventional chemotherapeutic drug cisplatin." (PMID 41614754, 2025). "In this study, EZH2 inhibitors EPZ6438 and ZLD1039 have been investigated for their cytotoxicity, apoptosis induction, and cell cycle arrest following their exposure on HPV+ and HPV- cervical cancer cells." (PMID 41614754, 2025). "Targeting the EZH2–PTEN–AKT axis may provide a potential therapeutic approach to mitigate combined radioresistance and chemoresistance in recurrent cervical cancer, although further preclinical and clinical validation is required." (PMID 41156200, 2025). "Targeting EZH2 or DNMT3A and CCL22-CCR4 axis may impede the progression or metastasis of cervical cancer and enhance patient prognosis." (PMID 39513112, 2024). "Rescue assays showed that activation of the miR‐214/EZH2 regulatory loop either by overexpression of miR‐214 or by silencing of EZH2, both reverse the roles of LINC01535 in promoting cervical cancer cell growth, migration and invasion in vitro, and cervical cancer xenograft growth in vivo." (PMID 31273925, 2019). "For instance, PVT1 forms a complex with EZH2 and then recruits EZH2 to the promoter regions of miR-195 and miR-200b, increases the trimethylation of histone H3K27, and downregulates the levels of miR-195 and miR-200b in cervical cancer." (PMID 31497532, 2019). "Activation of the miR‐214/EZH2 regulatory loop by overexpression of miR‐214 or silencing of EZH2 reverses the roles of LINC01535 in promoting cervical canc`er cell growth, migration and invasion in vitro and cervical cancer xenograft growth in vivo." (PMID 31273925, 2019). "Studies show that the upregulation of PVT1 favors its binding to EZH2 (Enhancer of Zeste Homolog-2), a subunit of Polycomb Repressive Complex 2 (PRC2) to inhibit miR-200b expression by increasing histone H3 lysine 27 trimethylation (H3K27me2) on the miR-200b promoter in cervical cancer." (PMID 32117705, 2020). "However, the mechanisms of the EZH2-mediated promotion of the proliferation and tumor formation of cervical cancer cells have not been shown to involve the activation of Wnt/β-catenin signaling." (PMID 27092879, 2016). "Furthermore, EZH2 protein expression was detected by western blotting in 8 normal cervical specimens and 8 primary cervical carcinoma specimens." (PMID 27092879, 2016).
myeloid neoplasm (54 papers, 2011 to 2025). Proliferation of myeloid cells originating from a primitive stem cell. "Enhancer of Zeste Homolog 2 (EZH2) variants in myeloid neoplasms correspond to loss-of-function mutations and have been reported in approximately 5% of patients with MDS." (PMID 40565579, 2025). "EZH2 mutations are associated with oncogenesis and progression, and predict poor prognosis in patients with myeloid neoplasms." (PMID 36313674, 2022). "In myeloid neoplasms, EZH2 mutations have been described in patients with PV (3%), myelofibrosis (13%), CMML (6%), AML (6%) and MDS (10%); in MDS they have been associated with a worse prognosis." (PMID 35626091, 2022). "Mutational profiling revealed mutations in four genes associated with myeloid malignancies, namely, EZH2, CUX1, TET2, and BCOR." (PMID 33628448, 2021). "Mutations in the EZH2 gene are recurrently found in patients with myeloid neoplasms and are associated with a poor prognosis." (PMID 33845873, 2021). "At cellular level, NRasG12D induces myeloid lineage-biased differentiation and EZH2-deficiency impairs myeloid cell maturation, whereas they cooperate to promote myeloid neoplasms with dysregulated transcriptional programs." (PMID 34732703, 2021). "BCAT1, a transaminase for branched-chain amino acids, is upregulated by EZH2 loss in mouse models and human myeloid neoplasm samples." (PMID 32650416, 2020). "BCAT1 is repressed by EZH2 via H3K27me3 modification in normal hematopoietic processes but is abnormally activated in EZH2-deficient myeloid neoplasms in mice and humans." (PMID 32448308, 2020). "Overall, EZH2 aberrations in the form of mutations or altered expression play an important role in the pathogenesis of various myeloid malignancies." (PMID 32650416, 2020). "More recently, distinct cancer-associated mutations in EZH2 have been reported, including gain-of-function mutations in lymphoid malignancies and loss-of-function mutations in myeloid malignancies where they are also associated with a poor prognosis." (PMID 31552175, 2019). "Loss of EZH2 activity in myeloid malignancies also results from differential splicing in the presence of an SRSF2 mutation or consequent upon ASXL1 mutation." (PMID 31552175, 2019). "Although there is an obvious rationale for inhibiting EZH2 function in malignancies in which this gene is overactivated, the finding of inactivating mutations in myeloid neoplasms suggests that this approach will need to be employed with caution." (PMID 27471434, 2016). "We examined the impacts of loss-of-function EZH2 mutations on the pathogenesis of myeloid malignancies using Ezh2 conditional knockout mice and demonstrated that an Ezh2 deficiency in combination with a Tet2 hypomorph in mice accelerates the transformation of HSCs and induces MDS and MDS/MPN." (PMID 33292805, 2020). "However, as we have alluded to, EZH2 mutations cosegregate with other poor-risk characteristics, such as patient age and an increased likelihood of antecedent myeloid malignancy such as MPN or MDS." (PMID 30890554, 2019). "Meanwhile, EZH2 could also act as a tumor suppressor, since acquired EZH2 mutations in myeloid neoplasms have been identified." (PMID 29156711, 2017). "Homozygous inactivating EZH2 mutations were detected in a portion of myeloid malignancies, raising the possibility that EZH2 may either exert pro- or anti-oncogenic activities, in a cell type-dependent manner." (PMID 21765901, 2011). "Additionally, EZH2 mutations were associated with poor overall survival in myeloid neoplasms." (PMID 36300880, 2022). "However, a few studies also showed that coding mutations in EZH2 were present in various lymphoid and myeloid neoplasms, which implied that EZH2 could potentially have a tumor suppressive role." (PMID 27119045, 2016).
myeloid neoplasm (continued). "In the absence of these three major driver mutations, screening for other mutations associated with myeloid neoplasms, such as ASXL1, EZH2, TET2, IDH1, IDH2, SRSF2, and SF3B1, can help establish the clonal nature of the disease." (PMID 41514563, 2025). "In myeloid malignancies, EZH2 regulates CXXC5 expression and influences disease development, and the mutation status of EZH2 affects CXXC5 expression." (PMID 39806388, 2025). "Together, these data indicate that inactivation of Asxl1 and Ezh2 in HSPCs results in development of aggressive myeloid malignancies as observed in human patients." (PMID 40561338, 2025). "ETNK1 mutation is an early event in myeloid neoplasms, often co-occurring with ASXL1, TET2, EZH2, RUNX1, and SRSF2 mutations." (PMID 40074445, 2025). "Some investigations reported the co-occurrence of ASXL1 mutations with EZH2, IDH1/2, RUNX1, and TET2 in myeloid malignancies." (PMID 38807730, 2024). "Of note, ARCH is characterized by the presence of somatic mutations in genes that are also frequently mutated in SM (e.g., ASXL1, DNMT3A, EZH2, RUNX1, SF3B1, SRSF2 and TET2) and other myeloid neoplasms." (PMID 35626091, 2022). "In contrast, the role of EZH2 in myeloid malignancies is less well defined and at first glance counterintuitive." (PMID 30890554, 2019). "Our dataset contained neutral polymorphisms and mutations associated with myeloid malignancies from epigenetic regulators ASXL1, DNMT3A, EZH2, and TET2." (PMID 24348198, 2013). "Although a reduction of EZH2 levels and H3K27me3 can be achieved by DNA demethylation agents in combination with histone deacetylation inhibitors, it remains to be proved if such a therapeutic approach can be effective for EZH2-defective myeloid malignancies." (PMID 36835136, 2023). "The evaluation of EZH2 expression might favorably complement the routine molecular profiling of patients with myeloid neoplasms." (PMID 33845873, 2021). "For myeloid malignancies, the most prevalent mutations in epigenetic regulators are in TET2, isocitrate dehydrogenase 1 and 2 (IDH1, IDH2), additional sex combs-like 1 (ASXL1), enhancer of zeste homolog 2 (EZH2), and DNA methyltransferase 3A (DNMT3A)." (PMID 31731811, 2019). "Overexpression of EZH2 in myeloid malignancies suggests that it functions as an oncogene." (PMID 25313314, 2014). "EZH2 is frequently mutated in lymphoid malignancies, with the hot spot on Tyr641; however, mutations in myeloid malignancies are spread throughout the entire sequence with no hot spot." (PMID 24348198, 2013). "The loss of EZH2 in JAK2 V617F hematopoietic cells was shown to reduce H3K27me3 levels with an increase in H3K27 acetylation and the resulting activation of PRC2 target genes including High Mobility Group AT-Hook 2 (HMGA2), an oncogene previously implicated in PMF and other myeloid neoplasms." (PMID 32650416, 2020). "EZH2 gain-of-function mutations that enhance H3K27me3 levels are pathogenic for germinal center type large B cell lymphomas, whereas global loss of EZH2 function due to mutation/deletion of EZH2 or associated factors such as SUZ12, EED and ASXL1 are associated with myeloid neoplasms." (PMID 25188243, 2014). "Around 60% of CD34+ cells from patient 2 [P2(h)] exhibited a heterozygous JAK2V617F mutation (JAK2V617F/WT) whereas no mutation was identified in these cells in ASXL1 and the other genes involved in myeloid malignancies, including TET2, EZH2, DNMT3A, IDH1 and SRSF2." (PMID 24066127, 2013).
myeloid neoplasm (continued). "One preclinical study implicated EZH2 in the pathogenesis of a murine KMT2A-MLLT3 AML model, but generally, EZH2 does not seem to represent an important driver in the pathogenesis of myeloid neoplasms and is currently not considered a promising therapeutic target these diseases." (PMID 40374809, 2025). "Thus, it is not surprising that for EZH2—central in maintaining PRC2 activity—tumor suppressor function has been proposed when in 2010, inactivating point mutations in myeloid neoplasms were discovered by different groups." (PMID 33845873, 2021).
nasopharyngeal carcinoma (49 papers, 2011 to 2024). A carcinoma arising from the nasopharyngeal epithelium. "A recent study reported that GSK3β negatively regulates EZH2 expression in nasopharyngeal cancer cells, and the level of GSK3β phosphorylation at Ser9 is associated with higher EZH2 protein expression in patients with nasopharyngeal carcinoma." (PMID 27494834, 2016). "High EZH2 expression is associated with an undifferentiated cellular state in nasopharyngeal carcinoma patient samples." (PMID 27172794, 2016). "In an additional study, the authors explored the anti-tumor action of Dznep, an EZH2 inhibitor, in the setting of nasopharyngeal carcinoma (NPC) in human patients and in mouse models." (PMID 34930302, 2021). "In human nasopharyngeal carcinoma, EZH2 recruits DNA methyltransferase DNMT1 and induces hypermethylation in the promoter region of miR-142, thereby inhibiting its expression." (PMID 34386429, 2021). "MiR-26a was found to suppress cell growth and tumor development by inhibiting the expression of the enhancer of zeste homolog 2 (EZH2) accounting for the tumorigenesis of nasopharyngeal carcinoma." (PMID 33843426, 2021). "In nasopharyngeal carcinoma, miR-142-3p was downregulated by DNA methylation due to EZH2’s recruitment of DNMT1 which occupied the upstream region of the miR-142 and determined ZEB2 activation, leading to EMT and metastasis." (PMID 33014831, 2020). "Another reports that hsa-let-7a inhibits proliferation and induces apoptosis by targeting EZH2 in nasopharyngeal carcinoma cells." (PMID 31963559, 2020). "Let-7a inhibits cell proliferation and apoptosis by inhibiting EZH2 in nasopharyngeal carcinoma cells." (PMID 33718109, 2020). "H19 regulated EZH2 and promoted cell invasion by interacting with miR-630 in nasopharyngeal carcinoma." (PMID 31064820, 2019). "Much more generally, H19 was shown to induce an increase of EZH2 levels in nasopharyngeal carcinoma cells, by working as a “sponge” for miR-630, thus sequestering it from its target, EZH2 mRNA." (PMID 29643989, 2018). "In human nasopharyngeal carcinoma, EZH2 inhibits miR-1 transcription via promoter binding activity, leading to enhanced expression of Endothelin-1 (ET-1) which is suppressed by miR-1 targeting of ET-1 3’UTR." (PMID 29221202, 2017). "In nasopharyngeal carcinoma, long noncoding RNA H19 regulates EZH2 expression by interacting with miR-630 and promoted cell invasion." (PMID 29050269, 2017). "In nasopharyngeal carcinoma (NPC), elevated EZH2 levels were associated with an aggressive phenotype with poor prognosis and enhanced microvessel density." (PMID 28410242, 2017). "We found that expression of EZH2 correlated with phosphorylated GSK3β (p-GSK3β) at Ser 9 (an inactivated form of GSK3β) in human nasopharyngeal carcinoma (NPC) samples." (PMID 23874688, 2013). "Furthermore, Ribavirin modulates EZH2, Snail, and eIF4E in nasopharyngeal carcinoma (NPC), osteosarcoma, and glioma leading to decreased migration and adhesion." (PMID 34206772, 2021). "Interestingly, the EZH2 inhibitor EPZ-6438 showed synergistic effects on growth inhibition when combined with HDAC inhibition in nasopharyngeal carcinoma (NPC)." (PMID 34070716, 2021). "EZH2 plays a key role in cancer progression, and its function as a key regulator is studied in several cancers, such as breast, prostate and nasopharyngeal carcinomas." (PMID 32397507, 2020). "Differentiation of nasopharyngeal carcinoma cells was induced via inhibiting an epigenetic mechanism by which EZH2 (enhancer of zeste 2 polycomb repressive complex 2 subunit) represses IKKα (inhibitor of nuclear factor kappa-B kinase subunit beta) expression and impairs tumor cell differentiation." (PMID 31661894, 2019). "The role of GSK-3beta and EZH2 has been investigated in nasopharyngeal carcinoma (NPC)." (PMID 27999207, 2017).
nasopharyngeal carcinoma (continued). "Recently, significant downregulation of miR-26a was also reported in nasopharyngeal carcinoma tissues and cell lines; its ectopic expression has been shown to downregulate EZH2 expression, thereby inducing G1-phase cell-cycle arrest to decrease cell proliferation and colony formation." (PMID 26516699, 2015). "By silencing EZH2, the mRNA expression levels of E-cadherin and Keratin 18 increased by 177 and 158%, respectively; while mesenchymal markers, β-catenin and N-cadherin, decreased by 18.04 and 41.18%, respectively, in nasopharyngeal carcinoma cells." (PMID 25295088, 2014). "However, the signalling pathway underlying the regulation of EZH2 in nasopharyngeal carcinoma (NPC) remains unclear." (PMID 23874688, 2013). "In particular, HOTAIR was found to recruit EZH2 to the CDH1 promoter in nasopharyngeal carcinoma (NPC), leading to its transcriptional repression." (PMID 36509828, 2022). "β-Elemene could also inhibit the growth of C666-1 and HNE2 cells (nasopharyngeal carcinoma cells) associated with the inactivation of signal transducer and activator of transcription 3 (Stat3) and the reduced expression of DNMT1 and enhancer of zeste homolog 2 (EZH2)." (PMID 33801899, 2021). "H19 is also found to be overexpressed in nasopharyngeal carcinoma (NPC) and to promote NPC cell invasion capacity via E-cadherin silencing and miR-630/EZH2 regulation." (PMID 33123473, 2020). "Recently, Lu and colleagues reported that miR-26a is commonly downregulated in nasopharyngeal carcinoma (NPC) and functions by repressing EZH2 expression." (PMID 26057471, 2015). "LncRNA HOTAIR high-expression can inhibit the expression of E-cadherin by recruiting histonemethylase EZH2 to mediate H3K27 trimethylation, thereby affecting the progression of nasopharyngeal carcinoma." (PMID 38070058, 2023). "In nasopharyngeal carcinoma cells (NPCs), β-elemene inhibits DNA damage repair and NPC cell growth via inactivation of Stat3 and reduces DNMT1 and EZH2 expression." (PMID 37121970, 2023). "Interestingly, we noticed that the EZH2 amino acid sequence contains several glycogen synthase kinase 3 beta (GSK3β) phosphorylation motifs (Ser/Thr-X-X-X-Ser/Thr, where X represents any amino acid), and GSK3β and EZH2 interaction has been shown in nasopharyngeal cancer with unknown consequence." (PMID 27494834, 2016). "In previous studies, miR-26a/b have been shown to block the G1/S transition of the cell cycle by targeting CCND2, CCNE1/2, CDK6, and EZH2 in HCC and nasopharyngeal carcinoma, and to restrain metastasis by suppressing the expression of IL6 in HCC." (PMID 24565101, 2014). "However, the role of EZH2 in angiogenesis is still unknown in nasopharyngeal carcinoma (NPC)." (PMID 25237831, 2014). "Furthermore, miR-142-3p has been shown to be epigenetically inhibited by EZH2-recruited DNMT1, suppressing the metastasis of nasopharyngeal carcinoma." (PMID 38890707, 2024). "Moreover, upregulated EZH2 formed a co-repressor complex with HDAC1/HDAC2/Snail to inhibit E-cadherin which was responsible for the aggressiveness, invasion and metastasis of nasopharyngeal carcinoma cell." (PMID 24345883, 2013). "Moreover, EZH2 targeting seems to have a negative effect on the number of EBV LMP1-induced activated regulatory T cells, thus enhancing antitumor immunity in nasopharyngeal carcinoma." (PMID 34070716, 2021).